GPRC5D (G protein-coupled receptor class C group 5 member D)
Description:
G protein-coupled receptor involved in hard keratin expression and likely plays a role in the development of hair and nails.
Tractability: Small molecule: a structure with a bound ligand is known. Antibody: an approved drug acts on it; UniProt places it where antibodies can reach, with high confidence; UniProt predicts a signal peptide or a membrane-spanning region; its Gene Ontology location is reachable by antibodies, with medium confidence.
Target class: Family C G protein-coupled receptor; Membrane receptor
Gene: Protein-coding gene on chromosome 12 (12,940,575 to 12,952,170, reverse strand). Ensembl gene ENSG00000111291.
Subcellular location: Cell membrane
Gene Ontology:
Molecular function: protein binding; protein kinase activator activity; G protein-coupled receptor activity
Biological process: G protein-coupled receptor signaling pathway
Cellular component: extracellular exosome; plasma membrane; receptor complex; membrane
Genetic constraint (gnomAD): Loss-of-function variants: 14 observed, 25.37 expected, observed/expected ratio (o/e) 0.55, 90% interval 0.36 to 0.86. The upper end of that interval is the gene's LOEUF score, 0.86, which puts it in group 3 of 6, group 1 being the genes least tolerant of losing a copy. Missense variants: 314 observed, 385.41 expected, observed/expected ratio (o/e) 0.81, 90% interval 0.74 to 0.89. Synonymous variants: 155 observed, 158.28 expected, observed/expected ratio (o/e) 0.98, 90% interval 0.86 to 1.12.
Homologues: Orthologues: chimpanzee GPRC5D (99% identical), macaque GPRC5D (96% identical), dog GPRC5D (85% identical), pig GPRC5D (84% identical), rabbit GPRC5D (83% identical), guinea pig GPRC5D (83% identical), mouse Gprc5d (81% identical), rat Gprc5d (79% identical), tropical clawed frog gprc5a (43% identical). Paralogues in human: GPRC5A (44% identical), GPRC5C (35% identical), GPRC5B (32% identical).
Diseases named in the same sentence as GPRC5D in open-access papers:
GPRC5D is named in the same sentence as 16 diseases in open-access papers, as found by Europe PMC text mining. Sharing a sentence is not in itself a finding about the gene and the disease. The quoted sentences say what the papers report.
myeloma (58 papers, 2019 to 2026). "Other studies demonstrated that loss of BCMA and GPRC5D is observed in 4% and 35% myeloma patients after treatment with BCMA CAR-T and GPRC5D CAR-T, respectively." (PMID 39013849, 2024). "GPRC5D is overexpressed in poor-risk myeloma, whereas only low expression is detected in normal tissues, except in hair follicles." (PMID 34572927, 2021). "Immunotherapies targeting surface antigens have transformed the treatment landscape of multiple myeloma (MM), with GPRC5D emerging as a promising therapeutic target." (PMID 41917280, 2026). "The most promising targets in the advanced stage of clinical development include GPRC5D and FcRH5, which demonstrate high specificity to myeloma cells, the favorable safety profile, and efficacy in patients who had earlier received BCMA-specific therapy." (PMID 40649828, 2025). "To facilitate comparison, we have summarized the core structural and pharmacological properties of the major BCMA- and GPRC5D-directed T cell engagers in multiple myeloma." (PMID 41470115, 2025). "The expression of GPRC5D on the surface of myeloma cells in all patients was detected with flow cytometry before induction therapy, and patients were stratified into high and low GPRC5D expression groups based on the median GPRC5D positivity rate." (PMID 40425453, 2025). "The study revealed GPRC5D as a new target for bispecific therapy in myeloma, with a safety profile that included lower grade 3–4 infection rates compared to BCMA-targeting agents (20–26%)." (PMID 40940825, 2025). "In myeloma cell lines, GPRC5D expression is inversely correlated with the methylation level of its regulatory region." (PMID 41439209, 2025). "There are several ongoing GPRC5D-directed CAR T-cell studies in myeloma, and prior studies have already demonstrated high rates of GPRC5D expression in MM and AL amyloid." (PMID 40264764, 2025). "Talquetamab can bind to GPRC5D, a biomarker associated with high-risk myeloma, and CD3, and induces T-cell mediated death of myeloma cells expressing GPRC5D via recruitment and maturation of T-cells." (PMID 39982274, 2025). "The expression of G protein‐coupled receptor, class C Group 5 member D (GPRC5D), on the surface of myeloma tumor cells makes it a possible target for relapse/refractory multiple myeloma therapy, and relevant studies are in progress." (PMID 40095426, 2025). "Existing results of CAR‐T targeting GPRC5D in the treatment of relapsed/refractory multiple myeloma." (PMID 40095426, 2025). "Bispecific antibodies are drugs that bind to two different antigen sites simultaneously, typically CD3 of T cells and tumor antigens (BCMA/FCRh5/GPRC5D) of the myeloma cells enhancing anti-tumor activity of host immune cells." (PMID 39754658, 2025). "The selective expression in Multiple myeloma cells suggests that GPRC5D is an ideal target for immune effector cell‐mediated therapy to treat Multiple myeloma." (PMID 40914945, 2025). "The existing preclinical studies and clinical trial results collectively suggest that GPRC5D‐targeted CAR‐T cells offer significant potential for patients with multiple myeloma, particularly those who relapse following anti‐BCMA treatment." (PMID 41439209, 2025). "The review aims to systematically summarize the current advancements in GPRC5D‐targeted therapies for multiple myeloma, thereby providing valuable insights and a foundation for future studies." (PMID 40095426, 2025). "Talquetamab is a bispecific mAb that targets CD3 and GPRC5D and was approved for the treatment of multiple myeloma in August 2023." (PMID 39982274, 2025). "Talquetamab is the first bispecific antibody targeting the non-BCMA antigen G-protein-coupled receptor class C group 5 member D (GPRC5D), which is highly expressed on myeloma cells." (PMID 41470115, 2025). "GPRC5D expression that is limited to hair follicles and skin made it a promising immunotherapeutic target in multiple myeloma." (PMID 39941892, 2025).
myeloma (continued). "GPRC5D’s high expression stability in myeloma cells and its accessibility on the tumor surface facilitate quick and effective interactions with CAR cells, ensuring reliable activation of the effector response." (PMID 40649828, 2025). "Talquetamab is the first G protein-coupled receptor family C group 5 member D (GPRC5D) × CD3 bispecific antibody approved for relapsed/refractory multiple myeloma (RRMM)." (PMID 41405810, 2025). "GPRC5D, an orphan G‐protein‐coupled receptor, is highly expressed on the surface of tumor cells in over 50% of patients with myeloma." (PMID 41439209, 2025). "G‐protein‐coupled receptor, class C group 5 member D (GPRC5D), an orphan G‐protein‐coupled receptor, is highly expressed on the surface of tumor cells in over 50% of patients with myeloma." (PMID 41439209, 2025). "A preclinical study demonstrated that CAR-T cell therapy targeting both BCMA and GPRC5D can reduce relapse caused by BCMA antigen escape and eliminate BCMA-negative multiple myeloma cells in a mouse model." (PMID 40547010, 2025). "GPRC5D-targeting T-cell–redirecting therapies, as monotherapy or in combination with other anti-myeloma agents, will expand the number of treatment options available for patients with MM." (PMID 38307865, 2024). "To guide the design and development of new-generation antibody therapeutics for treating multiple myeloma, we attempted to elucidate the structure of an antibody in complex with the human GPRC5D." (PMID 38898050, 2024). "Additional trials are currently underway investigating the safety and efficacy of combining GPRC5D-targeting T-cell–redirecting agents with other anti-myeloma agents in patients with relapsed/refractory MM." (PMID 38307865, 2024). "Taken together, the encouraging safety and efficacy data from early phase anti-GPRC5D CAR T trials have propelled GPRC5D forward as the next promising therapeutic target moving closer to regulatory approval in myeloma." (PMID 38800372, 2024). "Recent results from a Phase I clinical trial (NCT04555551) of CAR‐T cell therapy (MCARH109) targeting GPRC5D confirmed that GPRC5D is an important immunotherapeutic target in multiple myeloma." (PMID 38783893, 2024). "Combined with mutagenesis and functional experiments, we aim to leverage these structural insights to guide the development of antibody therapeutics targeting GPRC5D, addressing the current gap in the treatment of multiple myeloma." (PMID 38898050, 2024). "G-protein-coupled receptor class 5 member D (GPRC5D) is detected in malignant plasma cells in approximately 90% of patients diagnosed with multiple myeloma (MM)." (PMID 38429446, 2024). "AEs related to GPRC5D expression on non-myeloma cells were mostly grade 1/2, including skin-related AEs, mucosal AEs, and hair and nail changes." (PMID 38307865, 2024). "Recent research has revealed the highly specific and augmented expression of GPRC5D on the surface of multiple myeloma cells, thereby establishing it as an attractive target for antibody-based therapies against MM20." (PMID 38898050, 2024). "G protein–coupled receptor class C group 5 member D (GPRC5D) has emerged as a novel therapeutic target for the treatment of multiple myeloma." (PMID 38307865, 2024). "The most common grade 3 or higher adverse events (AEs) included neutropenia (94%), thrombocytopenia (65%), and anemia (35%), which confirm that GPRC5D is an active immunotherapeutic target in multiple myeloma." (PMID 38961036, 2024). "While BCMA is expressed on all mature plasma cells, GPRC5D is selectively expressed on the surface of myeloma cells, making it an attractive target for immunotherapy against abnormal plasma cells." (PMID 37296856, 2023). "GPRC5D is a surface receptor that is expressed on various bone marrow plasma cells and myeloma cell lines from patients with MM." (PMID 38006053, 2023). "Several bispecific antibodies (bsAbs) targeting BCMA, GPRC5D, and FcRH5 are in clinical trials for heavily pretreated multiple myeloma (MM) patients." (PMID 37537597, 2023).
myeloma (continued). "G protein–coupled receptor, class C group 5 member D (GPRC5D) is considered to be a promising surface target for multiple myeloma (MM) immunotherapy." (PMID 36881785, 2023). "Preliminary results from an ongoing phase 1 study of an anti-GPRC5D CAR OriCAR-017 (NCT05016778) were recently presented in 9 patients with R/R myeloma, including patients previously treated with anti-BCMA CAR T therapies." (PMID 36389674, 2022). "A phase I clinical trial currently investigates GPRC5D-directed CAR-T cell therapy (MCARH109) in relapsed/refractory multiple myeloma, including patients who have received prior BCMA-targeted therapies (NCT04555551)." (PMID 34572927, 2021). "GPRC5D, a myeloma cell surface antigen whose precise function remains to be defined, has recently been proposed as an attractive candidate for anti-myeloma CAR-T cell therapy." (PMID 31379824, 2019). "Hence, GPRC5D holds a prominent place among promising targets for cellular therapy of multiple myeloma, namely in patients with resistivity or relapsing after BCMA-specific therapy." (PMID 40649828, 2025). "Challenges of targeting GPRC5D in the treatment of relapsed/refractory multiple myeloma." (PMID 40095426, 2025). "These molecules are engineered to simultaneously bind to a tumor-associated antigen [such as BCMA or G protein-coupled receptor, class C group 5 member D (GPRC5D)] on myeloma cells and CD3 on T cells, thereby redirecting T-cell cytotoxicity against malignant plasma cells." (PMID 40940825, 2025). "Furthermore, a phase 1 clinical study in 2024 demonstrated that anti-BCMA/GPRC5D bispecific CAR T-cell therapy is a promising treatment modality for multiple myeloma, suitable for patients with relapsed or refractory multiple myeloma (R/R MM)." (PMID 40547010, 2025). "This unique expression pattern makes GPRC5D a promising therapeutic target for myeloma." (PMID 41439209, 2025). "Similarly, Talquetamab targets GPRC5D on myeloma cells and has been approved for r/r multiple myeloma." (PMID 40950404, 2025). "Furthermore, GPRC5D is minimally expressed in bone marrow samples of other hematologic malignancies, making it a promising immunotherapeutic target for treating multiple myeloma patients." (PMID 40547010, 2025). "Talquetamab is an anti-GPRC5DxCD3 BsAb also approved for multiple myeloma, with the notable difference of targeting GPRC5D, an orphan receptor which is expressed on malignant plasma cells, unlike BCMA, which is expressed on malignant and healthy plasma cells, and mature B lymphocytes." (PMID 39861922, 2025). "Besides being expressed by myeloma cells, GPRC5D is found in keratinized tissues such as hair follicles, skin, and lingual filiform papillae." (PMID 40277794, 2025). "Besides binding CD3 on T cells with one arm, the second one specifically binds to G-protein-coupled receptor family C, group 5, member D (GPRC5D), an orphan receptor present on the surface of normal plasma cells and myeloma cell lines." (PMID 39766080, 2024). "Studies have confirmed that GPRC5d is consistently expressed on MM cells with a membranous pattern and is absent from nearly all healthy tissues, with the exception of the hair follicle, making it an ideal target for anti-myeloma therapy." (PMID 38660139, 2024). "AEs related to GPRC5D expression on non-myeloma cells were mostly grades 1–2, including skin-related AEs (78% in IV cohort and 86% in SC cohort), mucosal AEs (73% in IV cohort and 77% in SC cohort), and hair or nail changes (23.5% in IV cohort and 28% in SC cohort)." (PMID 39001399, 2024). "Moreover, in a clinical study (ChiCTR210048888) of multiple myeloma (MM), GPRC5D was found to be a new alternative target, with GPRC5D CAR‐T cells playing a prominent role in MM patients not responding to BCMA CAR‐T cell therapy or patients with recurrence after treatment." (PMID 38456710, 2024).
myeloma (continued). "Multiple myeloma (MM) resistant to CD38 antibodies, two immunomodulatory drugs (IMiDs), two proteasome inhibitors (PIs), and both BCMA- and GPRC5D-directed immunotherapies defines hepta-refractory MM, a novel end-stage entity." (PMID 41703032, 2026). "JNJ-79635322 is a TsAbs developed for management of multiple myeloma, with a novel BCMA, GPRC5D, and CD3 T-cell redirecting antibody." (PMID 40227768, 2025). "A previous clinical study has shown that anti-BCMA/GPRC5D bispecific CAR-T cells exhibit good safety and promising activity in patients with relapsed or refractory multiple myeloma." (PMID 40547010, 2025). "The BsAbs simultaneously bind to a tumor antigen BCMA or GPRC5D expressed on myeloma cells and to CD3 on the T cells, resulting in the redirection of T cells to myeloma cells with subsequent T cell activation, leading to tumor cell death." (PMID 39941892, 2025). "Second-generation anti-BCMA CAR T cell therapies and bispecific antibodies that bind the tumor antigen BCMA or GPRC5D onto myeloma cells and CD3 on the T cell’s surface are currently available for the treatment of relapsed/refractory multiple myeloma." (PMID 39941892, 2025). "In hematologic malignancies such as multiple myeloma, where BITEs such as teclistamab (CD3 x BCMA), elranatamab (CD3 x BCMA) and talquetamab (CD3 x GPRC5D) are approved, potential mechanisms of resistance have been identified." (PMID 41413213, 2025). "Various target antigens, including BCMA, CD19, CD38, CD44v6, CD138, GPRC5D, kappa light chain, FcRH5, CS1, integrin β7, and NKG2D, have been used to engineer CAR T cells to kill myeloma cells, with encouraging results." (PMID 40078993, 2025). "Several plasma cell-specific antigens at the surface of myeloma cells have been studied as targets for TCEs, including B-cell maturation antigen (BCMA), G protein-coupled receptor, class C group 5 member D (GPRC5D), and Fc receptor-homolog 5 (FcRH5)." (PMID 40277794, 2025). "Bispecific antibodies developed for multiple myeloma currently target B-cell maturation antigen (BCMA), G protein–coupled receptor, class C, group 5, member D (GPRC5D), Fc receptor-like 5 (FcRL5), or CD-38." (PMID 39754658, 2025). "Although it is not known if these mechanisms are involved in relapse after anti-GPRC5D CAR T cell therapy, these studies highlight the complex nature of myeloma tumor biology and requirement of layered treatment strategies to thwart resistance." (PMID 38800372, 2024). "G protein-coupled receptor family C group 5 member D (GPRC5D) shows high and selective expression on multiple myeloma cells and is a target for immunotherapeutic treatments." (PMID 38530400, 2024). "Talquetamab, a bispecific IgG4 antibody that binds to both GPRC5d and CD3 to induce killing of GPRC5d-expressing myeloma cells by means of T-cell-mediated cytotoxicity." (PMID 38660139, 2024). "In the context of Multiple Myeloma, notable antigens such as CD19, CD38, CD138, BCMA (B-cell Maturation Antigen), Kappa (κ) light chain, SLAMF7, NKG2D, and GPRC5D have been identified as effective targets for CAR T-cell therapy." (PMID 38438559, 2024). "As a consequence, there is increasing interest in combinatorial immunologically based strategies that employ BCMA with other validated myeloma targets, such as CD38, SLAMF7, and CD19 or with emerging viable targets like GPRC5D." (PMID 37958658, 2023). "Bispecifics targeting antigens beyond BCMA, such as GPRC5D (GPRC5DxCD3, talquetamab, and RG6234) and FcRH5 (FcRH5xCD3, cevostamab), are in clinical development showing promising results for heavily treated myeloma." (PMID 37296856, 2023). "GPRC5D is highly expressed in malignant plasma cells, and the GPRC5D × CD3 bispecific antibody, JNJ-64407564, demonstrated potent antigen-specific T-cell–mediated cytotoxicity against myeloma cells in vitro and induced tumor regression in xenograft models." (PMID 41511330, 2025).